IL6 (interleukin 6)
Diseases named in the same sentence as IL6 in open-access papers (continued):
Sharing a sentence is not in itself a finding about the gene and the disease.
colorectal cancer (continued). "In colorectal cancer, açaí decreased myeloperoxidase (MPO) and cytokines such as tumor necrosis factor alpha (TNF-α), interleukin 1 beta (IL-1β) and interleukin 6 (IL-6), and inhibited cyclooxygenase 2 (COX-2), also reinforcing its anti-inflammatory effect." (PMID 40343252, 2025). "Our data demonstrate that QFG downregulates TNF-α, IL-6, and NF-κB expression in colon tissue, which is consistent with previous studies showing that QFG inhibits pro-inflammatory signaling in colorectal cancer." (PMID 40883855, 2025). "Our results showed that the concentrations of IL‐6, TNF‐α, and TGF‐β1 in the serum of NSD2fl/fl‐Vil1‐Cre mice with colorectal cancer were much lower than those in the serum of WT mice." (PMID 38400589, 2025). "Inflammatory biomarkers, including CRP, IL-6, TNF - α and its receptors, adiponectin and leptin, play complex roles in colorectal cancer development." (PMID 39980561, 2025). "This study investigates the association between Fusobacterium nucleatum presence and the expression of inflammation-related genes (IL6, IL1B, IL10, IL17, TNF) in tumor and matched normal tissues from Kazakhstani patients with colorectal cancer." (PMID 41267807, 2025). "In colorectal cancer, HIF-1α/miR-338-5p/IL-6 axis activation in response to hypoxic conditions is also reportedly conducive to tumor growth." (PMID 38440120, 2024). "The authors observed increased expression of IL-10 and IL-13 and decreased expression of IL-1β, IL-6, interferon gamma (IFN-γ), TNF-α, IL-12, and IGF-1 in peripheral blood mononuclear cells (PBMCs) derived from patients with colorectal cancer." (PMID 38957737, 2024). "Additional studies have observed that curcumin inhibits IL-6/JAK/STAT3 signaling by significantly reducing the phosphorylation of JAK2 and STAT3 levels in colorectal cancer (CRC) cells." (PMID 38673967, 2024). "Inflammatory cytokines, such as tumor necrosis factor-α (TNF-α) and interleukin-6 (IL-6), in intestinal epithelial cells significantly contribute to inflammatory bowel disease (IBD) and colorectal cancer (CRC)." (PMID 39451248, 2024). "It was found that Th17-type cytokines, IL-6 and TNF-α synergistically activate STAT3 to promote the growth of colorectal cancer cells." (PMID 38710698, 2024). "Interleukin-6 a pleiotropic cytokine involved in immune regulation and activation of JAK2/STAT3 pathway in colorectal cancer." (PMID 38869738, 2024). "In colorectal cancer, CAFs promote M2 macrophage polarization and recruitment by upregulating VCAM-1 expression in CRC cells and secreting chemokines IL-6 and IL-8/CXCR2 pathways, while also inhibiting NK cell function." (PMID 39068459, 2024). "In an in vivo model of AOM/DSS-induced colorectal cancer in C57BL/6 mice, 50 mg/kg and 100 mg/kg OLE reduced IL-6, TNF-α, and IFN-γ colon tissue levels, as well as COX-2 levels." (PMID 38540115, 2024). "IL-6 has been recognized as a potent inducer of CRC progression, including the induction of EMT in HCT116 human colorectal cancer cells." (PMID 38612842, 2024). "For example, colorectal cancer-derived mesenchymal stem cells promoted EMT and increased the migration and invasion of colorectal cancer by activating IL-6/JAK2/STAT3 signaling." (PMID 38182570, 2024). "CSCs from MC38 colorectal cancer and MC38-derived tumors showed that THF inhibited CSC formation and induced apoptosis of MC38-derived CSCs through the c-Myc/BRD4/PD-L1/RelB/IL6 axis." (PMID 37924094, 2023). "IL-6 activates autophagy through the upregulating JAK2 pathway and promotes chemotherapy resistance in colorectal cancer." (PMID 36751636, 2023). "In terms of miR-139-5p role in inflammation, overexpression of miR-139-5p was found to inhibit MMP9, MMP7, cell proliferation, and pro-inflammatory cytokines (IL-1β, IL-6, TNF-α) in colorectal cancer cell lines." (PMID 37474869, 2023).
colorectal cancer (continued). "The elevated proinflammatory cytokines, namely, IL-1β and IL-6, can be considered markers of POC in colorectal cancer." (PMID 38098074, 2023). "Inducing the EMT process and angiogenesis, the IL-6/STAT3 signaling acts an important effect in many solid tumor progressions, such as hepatocellular carcinoma and colorectal cancer 38-42." (PMID 37781036, 2023). "As far as we know, this is the first study in which serum levels of pro-inflammatory cytokines (IL-1β, IL-6, TNF-α), inflammatory markers (ESR CRP and fibrinogen), and tumor markers (CEA and CA 19.9) have been compared in colorectal cancer." (PMID 38137862, 2023). "Meanwhile, in colorectal cancer, IL1R2 is involved in activating IL6, VEGFA, and MEK/ERK, promoting cell proliferation and metastasis, promoting tumor angiogenesis, and enhancing tumor drug resistance." (PMID 37728418, 2023). "The inhibitors of miRNAs-221/-222 in colorectal cancer reduced cell growth and colony formation and STAT3 and IL-6 activity." (PMID 36816749, 2023). "IL6 mediates neutrophil mobilization from bone marrow, and IL8 enhances neutrophil recruitment for increased colorectal cancer cell death." (PMID 37013960, 2023). "IL-6 also enhances the chemoresistance via the STAT3 pathway in esophageal or gastric cancer and via the JAK2/BECN1 pathways in colorectal cancer." (PMID 35327514, 2022). "It inhibits the IL-6 cellular pathway and suppresses the expression of TNF, which has therapeutic effects on mouse colorectal cancer models." (PMID 36193082, 2022). "IL-6/STAT3-mediated miR-34a repression promotes and maintains invasiveness and metastasis in human colorectal cancer cells." (PMID 35740998, 2022). "Consistent with our findings, histidine level was negatively related to indicators of systemic inflammation, such as NLR, IL-6, and CRP, in patients with colorectal cancer." (PMID 35371012, 2022). "SAA expression was promoted by IL-22 in normal mouse cells, by lipopolysaccharide (LPS) in mouse colorectal cancer cell lines, as well as by a combination of IL-1ß, IL-6, and tumor necrosis factor-α (TNF-α) in human colorectal cancer cell lines." (PMID 35303008, 2022). "IL6 and CXCL8 present MSCs culture-conditioned media induced expression of OCT4 and SOX2 in colorectal cancer cells and promoted tumor progression via adenosine monophosphate protein kinase (AMPK)-mediated NF-κB activation." (PMID 35629138, 2022). "IL-6 enhances the proliferation of colorectal cancer cell lines in vitro, resulting in an increase in NF-kB and STAT3, which induce colorectal cancer cell growth." (PMID 36289922, 2022). "It has been reported that, in human colorectal cancer (CRC) cells, IL-6, another proinflammatory cytokine, activates the STAT3 transcription factor by directly repressing miR34A, leading to IL-6-induced EMT and invasion." (PMID 35267528, 2022). "The colorectal cancer cell line (HCT116) was induced by LPS/TNF-α and the inflammation and metastatic mediators (IL-1β, IL-6, IL-17) were quantified in calcitriol and capric acid supplemented colon cancer cells." (PMID 36235161, 2022). "According to the findings obtained from combined treatment of resveratrol and 5-FU, it was found that resveratrol reduces phosphorylated NF‐κB, IκBα, and IKK levels as well as MMP-9, COX-2, IL-6, and TNF-α levels in colorectal cancer cells." (PMID 35366874, 2022). "For example, Th17 type cytokines, IL-6 and TNF-α can synergistically activate STAT3 and NF-κB pathways to promote the growth of colorectal cancer cells." (PMID 35842665, 2022). "Knockdown of IL-21, which is overexpressed in human colorectal cancer and CAC mice, can reverse the overexpression of IL-6 and IL-17A in CAC mice." (PMID 36339623, 2022). "In summary, levels of IL-6, TNF-α and IL-12P7 in plasma of patients with advanced colorectal cancer increased." (PMID 36226059, 2022).
colorectal cancer (continued). "Knowing that interleukin-6 (IL-6) and C-reactive protein (CRP) factor into the development of colorectal cancer (CRC), we aimed to assess IL-6 and CRP's relationship with the stage and differentiation of CRC." (PMID 33552492, 2021). "In colorectal cancer, F. nucleatum promotes a NF-κB-driven proinflammatory genetic signature, including tumor necrosis factor (TNF) and interleukin-6 (IL-6) gene expression, cytokines that are also important in intestinal inflammation." (PMID 33653893, 2021). "A connection was observed in the colorectal cancer cell lines Colo205 and HT-29, in which the SPINK1 level was increased by both fibroblast-derived and recombinant IL-6 treatment." (PMID 33916984, 2021). "Inflammatory molecules such as IL-6, IL-8, IL-1β, and TNF-α have been shown to contribute to senescence and cancer initiation and progression in multiple cancers including breast and colorectal cancers, and IL-6 is a therapeutic target in ovarian cancer." (PMID 34588424, 2021). "A study confirmed that STAT3 is essential for proliferation and survival in colon cancer-initiating cells, and the IL-6/STAT3 pathway regulated the proliferation and contributed to the survival in colorectal cancer." (PMID 34165442, 2021). "Colorectal cancer cells exposed to IL-6 suppressed EMT transcription factor expression, as well as the invasion, and metastasis of the cancer cells by repressing IL-6 through expression of miR-34a." (PMID 34722553, 2021). "Studies have shown that cytokines IL-6 and IL-8 secreted from M2 macrophages produced via the MAPK pathway result in enhanced migratory and invasive abilities of colorectal cancer cells." (PMID 34063667, 2021). "Researchers have found that the FOLFOX chemotherapy regimen in a colorectal cancer model activated NF-κB, subsequently increasing the production of TNF and IL-6 and consequently leading to local inflammation and mucosal damage." (PMID 34412621, 2021). "In the present study, we demonstrate that IL-6 activates autophagy through the IL-6/JAK2/BECN1 pathway and promotes chemotherapy resistance in colorectal cancer (CRC)." (PMID 34131122, 2021). "In a mouse model of colorectal cancer, the use of AUR and its derivatives dramatically lowered the expression level of pro-inflammatory cytokines such as TNF-α, IL-1, and IL-6 and suppressed the activity of NF-κβ." (PMID 35432798, 2021). "Under the TNFα overexpression, significant upregulation of two genes was observed: proinflammatory cytokine IL6 gene in melanoma cells A375 and gene for pro-apoptotic ligand TRAIL in colorectal carcinoma cells HT29, both mediated by TNFα/TNFR1 signaling." (PMID 33957885, 2021). "Sixty percent IL-10−/− mice develop colorectal cancer; these mice have significantly increased levels of pro-inflammatory cytokines (IFN-γ, TNF-α, IL-1β, and IL-6), indicating the chronic intestinal inflammation related with the tumor growth." (PMID 32670290, 2020). "For example, decreased expression of miR155-5p has been shown to increase the expression of C/EBPβ and IL6 in TAMs, which in turn leads to activation of the IL6R/STAT3/miR-204-5p pathway and induction of chemoresistance in colorectal cancer cells." (PMID 33114182, 2020). "Gene expression of ALOX15 suppresses the TNF-α signaling pathway, IL-1β/NF-κB, and IL-6/STAT3, which play a major role in increasing colorectal cancer through chronic inflammation." (PMID 32986357, 2020). "The SHP1 agonists SC-43 and SC-78 stimulate SHP1 to deactivate IL-6-induced STAT3 phosphorylation, thereby inhibiting colorectal cancer stem cells." (PMID 32792945, 2020). "While it is known that IL-6 promotes the EMT of cancer cells, our study showed that IL-10, secreted by M2-TAMs, induced EMT in colorectal cancer cells." (PMID 32222879, 2020). "In colorectal cancer patients, white blood cell count, platelet, ApoA, FFA, IL-6 and TNF-α increase significantly, while albumin, prealbumin and ApoE decreased significantly." (PMID 31788012, 2019).
colorectal cancer (continued). "Patel and Gooderham observed that IL-6 triggers the IL-6R/STAT3 pathway and also increases miR-21 and miR-29b expression in colorectal cancer cells." (PMID 30884898, 2019). "We showed here higher serum levels of IL1B, IL6, CXCL8, TNFA, CCL2 and tumor levels of IL1B, IL6, CXCL8, TNFA in colorectal cancer, suggesting the involvement of these inflammatory factors in colorectal cancer." (PMID 31528237, 2019). "Mechanistically, we determined that interleukin-6 (IL-6) was the most highly expressed cytokine in the CC-MSC conditioned medium, and promoted the progression of colorectal cancer cells through IL-6/JAK2/STAT3 signaling, which activated PI3K/AKT signaling." (PMID 29348540, 2018). "The crosstalk of IL-6/STAT3 and SphK1/S1P/S1PR pathways has been suggested to play an essential role in the progression of inflammation related tumors, such as colorectal cancer." (PMID 29643998, 2018). "In our research IL-6 serum levels were statistically significantly different between controls and patients with CRC and showed marked increase with increasing stages of colorectal cancer." (PMID 30154846, 2018). "During the development of colorectal cancer in C57BL/6J-ApcMin/+ mice, increased IL-6 secretion in the interstitial fluid of the colorectal tissues was observed." (PMID 29707119, 2018). "an inflammatory cytokine, like interleukin-6 (IL-6), potentially triggers Fra-1 gene transcription by binding STAT3 to the promoter of Fra-1 gene in colorectal carcinoma (CRC) cells." (PMID 29914371, 2018). "Clinical studies have revealed that expression of TNF-α and IL-6 and activation of NF-κB and STAT3 are increased in patients with active UC and particularly in those who progress to colorectal cancer." (PMID 28300788, 2017). "Inflammation and pro-inflammatory cytokines produced by Th1 and Th17 cells like IL-6, TNF, IL-17 and IL-23 promote the development and growth of colorectal cancer (CRC)." (PMID 28881611, 2017). "MicroRNA-34a (miR-34a) is down-regulated in colorectal cancers (CRC) and required for interleukin-6 (IL-6)-induced CRC metastasis." (PMID 29108270, 2017). "Repression of BDKRB2, but not B1 receptor, attenuated the bradykinin-mediated invasion and migration in colorectal cancer cells, and inhibited ERK1/2 activation and IL-6 production." (PMID 28077802, 2017). "However, the interaction between MUC2 and IL-6 in colorectal cancer metastasis remains unclear." (PMID 28725043, 2017). "In pre-cachectic mice with transplanted colorectal cancer or autochthonous pancreatic ductal adenocarcinoma (PDA), we find that IL-6 reduces the hepatic ketogenic potential through suppression of PPARalpha, the transcriptional master regulator of ketogenesis." (PMID 27829137, 2016). "Enhanced expression of IL-6 and activation of STAT3 were observed in human colorectal carcinoma samples compared to normal colorectal tissue, with higher levels of IL-6/STAT3 in low grade carcinomas." (PMID 27006530, 2016). "Levels of IL-6, STAT3, and p-STAT3 were all increased in the human colorectal carcinoma samples, with a higher increase in low grade carcinoma." (PMID 27006530, 2016). "Before we analyzed the relationship between IL-6 and CEACAMs, we examined the expression of CEACAM5 and CEACAM6 in the normal mucosa-derived and colorectal cancer cell lines." (PMID 26673628, 2015). "Recent studies showed that Fusobacterium species increase production of reactive oxygen species (ROS) and inflammatory cytokines (e.g., IL-6 and TNF) in colorectal cancer." (PMID 25797243, 2015). "Proinflammatory cytokines (IL-1β, IL-6, IL-8, and TNF-α) are elevated in colorectal cancer (CRC), showing the presence of an active and permanent inflammatory state." (PMID 25945105, 2015). "The serum IL6 and IL8 levels were significantly increased in the colorectal cancer patients with liver metastasis." (PMID 25970784, 2015).
colorectal cancer (continued). "Specific inactivation of IL-6 signaling by antagonistic anti-IL-6 antibodies inhibited tumor growth, similar to the inhibition of TGF-β signaling in colorectal cancer." (PMID 23117246, 2013). "The aim of this study was to determine preoperative serum levels of VEGF, IL-6, and CRP in colorectal carcinoma, and to correlate them with disease status and prognosis." (PMID 20465852, 2010). "Others suggested that the pre-operative serum elevation of both IL-6 and CRP are good prognostic predictors in colorectal cancer patients." (PMID 19341447, 2009). "CT-26 murine colorectal carcinoma cells were stimulated with LPS, tumour necrosis factor α (TNF-α) and interleukin 6 (IL-6)." (PMID 17242699, 2007). "TNF-α and IL-6, which are pleiotropic cytokines, may have anti-tumour properties, and may be of benefit as chemotherapy agents in experimental cancer and even in the clinical treatment of colorectal cancer, and might act in synergy with conventional chemotherapeutics such as 5-FU." (PMID 12237767, 2002). "However, more recently published studies found a correlation between a high postoperative inflammatory response (CRP and interleukin-6) and worsened long-term survival in patients undergoing LAS and open surgery for UICC stage I–III colorectal cancer." (PMID 40383853, 2025). "Furthermore, adipose tissue is believed to modulate IL-6 and TNF receptors, exhibiting anti-inflammatory properties, while a meta-analysis of 55,391 patients in China found high BMI beneficial for colorectal cancer outcomes." (PMID 40387926, 2025). "This study investigated the immunomodulatory and therapeutic potential of betulin and its derivatives (EB5 and ECH147) in colorectal cancer (CRC), focusing on their effects on IL-6 expression at the molecular level and their possible application as diagnostic and therapeutic tools." (PMID 41256010, 2025). "Several reports have shown that IL-6 induces glycolysis in different types of cells including colorectal cancer cells, neuroblastoma cells, mouse fibroblasts and macrophages; however, the role of IL-6 in driving T cell metabolism has not been investigated." (PMID 40936905, 2025). "In our study, we also observed that SW1116 colorectal cancer cells exhibited higher IL-6 protein levels than non-cancerous cells, and that treatment with ECH147 significantly reduced this expression." (PMID 41256010, 2025). "In contrast, IL-6 was present in both the SW1116 colorectal cancer cells and the non-cancerous CCD-841CoN colon epithelial cells." (PMID 41256010, 2025). "Related to this, an increase in Akkermansia muciniphila following antibiotic treatment was found to elevate mRNA levels of pro-inflammatory cytokines IL-1β, IL-6 and TNF-α, promoting uncontrolled cellular proliferation and furthering colorectal cancer progression." (PMID 40520902, 2025). "Produces pro-inflammatory cytokines like IL-6 and TNF-α in specific conditions (e.g. colorectal cancer).Creates a pro-inflammatory microenvironment but may also impact adaptive immunity in disease states." (PMID 41050659, 2025). "WBE, capable of inhibiting the secretion of IL-1β, IL-6, and TNF-α in LPS-stimulated RAW 264.7 macrophages, may contribute to the attenuation of inflammation in colorectal cancer." (PMID 41463421, 2025). "Additionally, clinical data showed that plasma levels of IL-1β, IL-6, and TNF-α are significantly elevated in patients with colorectal cancer compared with healthy controls." (PMID 41463421, 2025). "In this study, we prepared postbiotics from IL6 targeting L. lactis displaying ZIL6 affibody on their surface with the long term aim to evaluate their therapeutic potential in inflammatory intestinal diseases and colorectal cancer." (PMID 41209739, 2025). "In a systematic review on gastrointestinal cancer, a high serum concentration of IL-6 was found to correlate with a poor prognosis in gastric, bile duct, and pancreatic cancers, but not in colorectal cancer." (PMID 39518029, 2024).